MIR520G (microRNA 520g)
Synonyms: hsa-mir-520g; MIRN520G; mir-520g
Gene: MicroRNA gene on chromosome 19 (53,722,166 to 53,722,255, forward strand). Ensembl gene ENSG00000207799.
Gene Ontology:
Biological process: miRNA-mediated post-transcriptional gene silencing